EGR1 (early growth response 1)
Diseases named in the same sentence as EGR1 in open-access papers (continued):
Sharing a sentence is not in itself a finding about the gene and the disease.
cancer (continued). "Furthermore, even though the importance of EGR1 is recognized with respect to cancer progression, the detailed mechanism regarding the action of NAB2 in association with EGR1 is largely unknown." (PMID 30845713, 2019). "However, there is little data showing that EGR1 directly inhibits cancer progression in vivo." (PMID 30845713, 2019). "In addition, EGR1 has been indicated in the induction of apoptosis in a variety of cancers." (PMID 29719592, 2018). "Considering gene therapy, the control of transgenic expression, via resveratrol activation, of Egr-1 promoter may sensitize cancer cells, extending the use of Ad.Egr-TNF to patients intolerant of radiation or chemotherapy, offering a novel tool for development of inducible gene treatments." (PMID 27148534, 2016). "Thus, our findings suggest that targeting the NOX2/Egr-1/Fyn pathway may have clinical implications within multiple cancer types; particularly where efficacy of TKI is compromised." (PMID 26136341, 2015). "EGR1 may induce or suppress cell proliferation or induce apoptosis of cancer cells." (PMID 21283769, 2011). "We examined whether EGR1 affects the expression of cancer invasion-related genes." (PMID 21283769, 2011). "It is noteworthy that EGR1 protein was up-regulated as early as 1 h after treatment with digitoxin at 0.1 μg/ml; since numerous factors can induce the expression of EGR1, it could be a sensitive target for cancer prevention or therapy." (PMID 21139994, 2010). "Within the constructed network, MMP1, KRT7, EGR1, and IL11 played crucial roles, likely due to the cell lines representing invasive and proliferative cancers." (PMID 41590789, 2025). "A recent study has indicated that EGR1, a key EGR family member, is crucial to cancer development and spread." (PMID 39866235, 2025). "Through RNA‐seq analysis, we have also shown differential expression of other cancer biomarkers by CHRDL2, such as EGR1, REG4 and TFF1, which have been shown to regulate proliferation, migration and metastasis." (PMID 40434957, 2025). "Numerous anti-cancer factors and pro-cancer factors are directly modified by NEDD8, and certain neddylation substrates such as CRL, EGR1, and HIF-1α can simultaneously regulate both types of factors." (PMID 39062453, 2024). "The expression of EGR1 and JUN influences cancer progression by regulating cell cycle processes and promoting cell proliferation." (PMID 38872167, 2024). "It has been reported that EGR1 regulates CDKN1A expression, resulting in the senescence of cancer cells." (PMID 39512814, 2024). "Disrupting the balance between EGR1 and NAB2 expression results in a high EGR1 transcriptional activity in cancer cells." (PMID 39120790, 2024). "Mechanically, EGR1 interacted with p300/CBP and combined to the promoter region of SNAI2, thus restrained E-cadherin expression and promoted cancer metastasis." (PMID 36932397, 2023). "In particular, our observations pointed to substantial suppression of EGR1, a downstream transcription factor activated by the MAPK-ERK signaling pathway in cancer." (PMID 37958905, 2023). "In detail, EGR1, TPP1, and SOCS2 conferred drug resistance, while RRM2 and C11orf54 exhibited drug sensitivity in pan-cancers." (PMID 35812443, 2022). "In some cancers, co-expression of IEGs, such as FOS, JUN, and EGR1, was positively correlated with poor survival." (PMID 36505794, 2022). "In pancreatic cancers, EGR1 binds to the Bax gene promoter to activate BAX expression, which subsequently leads to cancer cell apoptosis." (PMID 35563324, 2022). "Further analysis reveal that EGR1, TPP1, and SOCS2 confer drug resistance, while RRM2 and C11orf54 exhibit drug sensitivity in pan-cancers." (PMID 35812443, 2022). "A latest research showed that the expression of early growth response 1 (EGR1) and its downstream target carbonic anhydrase 9 (CA9), which were up-regulated in hypoxic cancers, are significantly increased in ectopic lesions." (PMID 36339404, 2022).
cancer (continued). "It has been reported that EGR1 is a downstream component of the MEK/ERK signaling pathway and can promote the cell cycle and invasion of cancer cells through this pathway." (PMID 34681812, 2021). "Among the TFs identified here in the response of aggressive CLL lymphocytes, EGR1 and EGR2 are zinc-finger TFs downstream of the Ras/Raf/MAP kinase pathway that is constitutively activated in various cancers and blood malignancies." (PMID 33833385, 2021). "Previous studies have shown that EGR1, TMEM79, and CRACR2A are closely related to the progression of a variety of cancers, and it is worthwhile to further explore their molecular mechanisms." (PMID 34853602, 2021). "Research suggests that vitamin D receptor, EGR1, and p300 synergistically initiate PTEN expression and apoptosis in cancer cells." (PMID 33842351, 2021). "Three EBSs have been identified in the enhancer region of BRCA1, and EGR1 is able to directly bind to the EBSs and to start BRCA1 gene expression thus initiating DNA repair and inhibiting cancer progression." (PMID 33842351, 2021). "EGR1 expression is increased by EBV LMP1 via NFKB and is required for EBV latent membrane protein 1 (LMP1)-induced cancer cell survival." (PMID 33114612, 2020). "EGR1 directly binds to the human IGF1R gene promoter, regulates its expression, activates the ERK and AKT pathways and promotes cancer cell growth." (PMID 32391121, 2020). "Data derived from The Cancer Genome Atlas (TCGA) showed that the expression of seven of these genes including EGR1 (early growth response protein 1) and FLNA (filamin A) significantly correlated with the therapy outcome in cisplatin-treated cancer patients." (PMID 32102425, 2020). "In collaboration with WT1/Early Growth Response 1 (EGR1), Bcl2 contributes to dysregulation of calcium homeostasis and signaling in cancer cells." (PMID 32856872, 2020). "Previous studies showed that EGR1 downregulates MMP2 and MMP9 by binding directly to their promoter in cancer cells." (PMID 30845713, 2019). "Collectively, these results indicate that Oct4 enhances the expression of Egr1 and its downstream gene OPN, thereby contributing to cancer metastasis." (PMID 31399076, 2019). "Recent studies have identified an additional role for CDK6 in the transcriptional regulation of cancer-relevant genes such as VEGF-A and EGR1 in hematopoietic malignancies." (PMID 30858922, 2019). "Ionizing radiation increases CLU promoter activity in cultured cancer cells, an effect mediated via EGR-1 and EGR-1 consensus sites." (PMID 30872998, 2019). "Over expression of EGR1 in ARMS led to a significant growth inhibition, consistent with results in many other cancers." (PMID 29719592, 2018). "Using multiple cohorts profile datasets and integrated bioinformatical analysis, we identified commonly 237 DEGs, and finally found EGR1, FOS, and FOSB, 3 cancer-related TFs, which were downregulated in HCC." (PMID 30228980, 2018). "We also examined the tumor suppressor and pro-apoptotic gene, phosphatase and tension homolog detected on chromosome 10 (PTEN), which is known to be activated by EGR1 and repressed by TBX2 in many cancer types." (PMID 29719592, 2018). "We found 237 differentially expressed genes (DEGs) including EGR1, FOS, and FOSB, which were three cancer-related transcription factors." (PMID 30228980, 2018). "Through regulating EGR1 and HOXB9, miR‐192‐5p downregulated the angiogenic pathways in cancer cells." (PMID 28035762, 2017). "Growth factors and serum induce the expression of EGR1 and SRF, respectively, which in turn induces UCP expression that positively regulated cancer cell growth in HeLa cells." (PMID 29246166, 2017). "The gene encoding TF can be transcriptionally upregulated in response to hypoxia, potentially via the early growth response-1 (EGR-1) transcription factor, in various cancer cells including EOC cells." (PMID 28417928, 2017).
cancer (continued). "The well-documented cancer-related genes NOTCH1, CDKN1A, EGR1, AKT3, TNF, MMP9, and SMARCA4 are located in the center of this newly constructed subnetwork." (PMID 28500316, 2017). "Sequence-specific transcription factors, such as early growth response protein 1 (Egr1) and SP1, can increase VEGF transcription in cancer cells." (PMID 26848522, 2016). "Three of these genes, JUN, EGR1, and AKAP12, are involved in the control of cell proliferation and cancer progression." (PMID 24961511, 2014). "Therefore, we treated cancer cells with inhibitors of actomyosin and adhesion molecules, and then analyzed ATF5 localization, EGR1 expression, JAK phosphorylation, and MYC expression." (PMID 40124511, 2025). "Targeting the recruitment of these complexes on gene promoters may be a promising therapy in several cancer types, since upon activation, ELK1 promotes the expression of several oncogenes including EGR1 and FOS." (PMID 40862737, 2025). "We further found that, unlike in cancer cells where EGR1 promotes SNAI1/SNAIL expression, its downstream in normal mammary cells appears to be distinct." (PMID 40204777, 2025). "Although this study provides a pan-cancer map of putative TF regulators, the prognostic and mechanistic relevance of central hubs, particularly MYC, TAF1, and EGR1, requires validation in future studies using independent, cancer type–specific cohorts such as those available from TCGA." (PMID 41155227, 2025). "In contrast, FOS, EGR1, and JUN inhibit apoptosis, exacerbating cancer progression." (PMID 40740774, 2025). "In addition, ATF5 suppressed the expression of early growth response 1 (EGR1), thereby accelerating cancer cell proliferation." (PMID 40124511, 2025). "EGR1 plays a central role in SFT and is involved in other types of cancers." (PMID 39120790, 2024). "EGR1 is regulated by CRL1, and its roles in cancer are cell-type-dependent." (PMID 39062453, 2024). "First, within the scope of scientific research, the role of EGR1 was not uniform across all types of cancer." (PMID 36932397, 2023). "In other instances, metabolic reprograming involves the synergistic interaction of SREBF2 with other transcription factors such as early growth response element 1 (EGR1) and the nuclear receptor RAR-related receptor gamma (RORγ) to promote cholesterol biosynthesis, particularly in cancer." (PMID 37745085, 2023). "However, ATGL regulates lipid metabolism in cancer cells in other pathways outlined in this review, namely, the HIF-1/HIG-2/ATGL axis, PPAR (PPAR-α and PPAR-γ)/G0S2/ATGL axis, and FSP-27/EGR-1/ATGL axis." (PMID 35912266, 2022). "Notably, among the genes downregulated upon DSCAM-AS1 knockdown were several proliferation activators of endometrial (and other) cancer cells, like NOTCH1, HMGA2, PTK2/FAK, FOSL1, GREM1 and EGR1." (PMID 35885035, 2022). "Moreover, we illustrated downstream‐targeted genes of JUN, FOS, FOSB, EGR1, and ZFP36 and demonstrated that these targeted genes were involved in “positive regulation of cell death”, “pathways in cancer”, “PI3K‐Akt signaling pathway”, and so on." (PMID 35037412, 2022). "Among these, the transcription factor EGR1 (a well-known immediate early gene) and LINC00473 (a primate-specific long non-coding RNA) that has emerged as an interesting RNA candidate involved in neuronal function and in cancer." (PMID 33198374, 2020). "The Src/ERK/Egr-1 signaling pathway is the most typical downstream pathway of IGF-1/IGF-1R, which participates in various physiological processes of cells as well as the occurrence and development of various cancers." (PMID 31661546, 2019). "Although previous studies have shown the paradoxical effect of EGR1 upregulated by EGF on cancer progression, none have reported on the molecular mechanisms that explain this phenomenon." (PMID 30845713, 2019).
cancer (continued). "Although KRT19 regulates EGR1/PTEN/AKT, β-catenin/NUMB/NOTCH, and HER2/ERK/SP1 cascades, we focused on the AKT, GSK3β, ERK, Src, and JNK signaling pathway in this study, as these signaling pathways are crucially involved in cancer progression." (PMID 29747452, 2018). "The results above suggested that EGR1, FOS, and FOSB, three cancer-related TFs, could play an important role in the progression of HCC." (PMID 30228980, 2018). "EGR-1/ASPP1, therefore, may be potentially used as therapeutic targets to improve cancer’s response to pro-apoptosis treatments." (PMID 28594407, 2017). "TOLE can inhibit cell growth in cancer cells through cyclooxygenase-independent pathways including inhibition of ErbB2 expression, activation or ATF3, or induction of NSAID-activated gene-1 (NAG-1) and EGR1." (PMID 29228577, 2017). "In carcinoma cells, a GC-rich NAB2 proximal promoter located within 600 bp upstream of the transcription start site (TSS) has been functionally defined, including several Egr1/Sp1 response elements." (PMID 29152069, 2017). "Pathway analysis of the 50 gene NIT signature revealed enrichment for MAPK signalling (DUSP1, JUN, NR4A1 and FOS), cancer specific (COX-2, PGE2, JUN and FOS), apoptosis induction (FOS and JUN) and genomic reformatting following (brain) ischaemia (EGR1 and JUN) pathways." (PMID 27384960, 2016). "Furthermore, an up-regulated inflammatory gene analysis identified the involvement of transcription factors, such as STAT4, EGR1, and FOSL1, which regulate cancer as well as inflammation in aging processes." (PMID 27153548, 2016). "Most importantly, our group have found SUMOylation has been linked to cancer initiation and development, for examples, SUMOylation of tumor suppressors PTEN, Egr1 and oncogenic protein Grb2 regulate tumorigenesis; SUMOylation of RhoGDI (Rho GDP-dissociation inhibitor) enhances cancer cell motility." (PMID 25823821, 2015). "Furthermore, strong correlations of PTGS2 or PTGES and EGR1 mRNA levels in several cancer datasets were found, and particularly in Skrzypczak Colorectal 2 dataset, Pearson's correlation was 0.84 for PTGS2 and EGR1 and 0.647 for PTGES and EGR1 mRNA levels." (PMID 26498686, 2015). "Thus, inhibition of HOXA10 can downregulate EGR1, PTEN, and Rad51 paralogs in serial order to interfere with the HR system of cancer cells, making the cancer cell more vulnerable to temozolomide treatment." (PMID 25061500, 2014). "Since activated Ras can stimulate ERK1/2 in many cancer types, we hypothesized that the Ras-GTPase inhibitor may block activation of ERK1/2 and expression of EGR1 and Snail in Tβ10-silenced CCA cell lines." (PMID 24053380, 2013). "The inappropriate chromatin reprogramming in the absence of EGR1 strongly support an important task for EGR1 in early epigenomic remodeling during chondrogenesis and pave the way for further studies on gene-environment interactions in development and cancer." (PMID 23483971, 2013). "Furthermore, the networks related to cell cycle, cancer and nervous system development and function showed that several genes such as Nfkb2, NFκBia, BRCA1, Vegf, Jag2, Notch1, EGR1, FoxS1 and collagen type I were regulated by TNF." (PMID 20967264, 2010). "Gene ontology, molecular network and canonical pathway analysis of NASP overexpression demonstrated that the most significant changes were in proteins participating in organismal injury, immune response, and cellular growth and cancer pathways (major "hubs": TNF, FOS, EGR1, NFκB, IRF7, STAT1, IL6)." (PMID 19439102, 2009). "In mouse models, the FMD synergistically improved the cancer-fighting impact of endocrine therapies, such as tamoxifen and fulvestrant, by significantly lowering systemic levels of IGF-1, insulin, and leptin, and impeding AKT–mTOR signaling pathways through the increased expression of EGR1 and PTEN." (PMID 38321992, 2024).
cancer (continued). "Using qPCR assay for known genes modulated NT157 in other cancer models, we identified that NT157 decreased expression of oncogenes BCL2, CCND1, MYB, and MYC and increased genes related to cellular stress and apoptosis, JUN, BBC3, CDKN1A, CDKN1B, FOS, and EGR1 (all p < 0.05)." (PMID 36224313, 2022). "We report that EGR1 is also upstream of E2-induced TGFβ1 transcription in primary human dermal fibroblasts, which is not surprising as EGR1 binds to and activates the TGFβ1 promoter and exogenous expression of EGR1 in the cancer cell line HT1080 led to increased secretion of TGFβ1." (PMID 33640015, 2021). "Furthermore, a comprehensive functional analysis of EGR1 targets revealed, among others, the enrichment of pathways related to intracellular signaling cascade controlling EGR1 expression itself (e.g. RAS and ERK) and proteoglycans in cancer." (PMID 34857011, 2021). "However, we previously determined that mindin attenuates CRC progression by blocking angiogenesis through Egr‐1–mediated regulation, and did not observe the direct suppression of human cancer cell proliferation and colony formation ability." (PMID 32614521, 2020). "Finally, stress-related mood disorders, schizophrenia, drug-related aspects, and cancer, in which EGR1 plays important roles, have no counterparts in ME/CFS." (PMID 33114612, 2020). "The reason for this paradoxal/antagonistic EGR1 function depending on cancer types is not clear." (PMID 32121305, 2020). "Interestingly, inhibition of EZH2 activity by EPZ-011989 also induced EZH2 protein down-regulation concomitantly with an increased expression of the known EZH2 target gene early growth response 1 (EGR1), a multifunctional transcription factor thought to act as a cancer suppressor." (PMID 31331120, 2019). "Four transcription factors, EGR1, HNF4A, MITF and FOXA2, appeared to form a hub of upstream regulators in all five gene-sets (p < 0.001) and could explain the apparent overlap in disease outcomes (ie. cancer)." (PMID 28531178, 2017). "Although further study is required, we can speculate that Egr-1 expression in endothelial cells is a specific process regulated by cancer-derived EVs rather than a general phenomenon." (PMID 25502753, 2014). "In addition, EGR1 and LCN2, which are known to instigate metastasis and angiogenesis, exhibited down-regulation, insinuating that Lipo-ICG phototherapy could counteract cancer metastasis." (PMID 38399278, 2024). "However, the change of cell viability by NTPAM showed even in EGR1 siRNA, suggesting that NTPAM-induced cancer cell death may be the result of simultaneous regulation of various molecules and EGR1 is at least one of the major factors for NTPAM-induced cell death." (PMID 33477921, 2021). "A decrease in expression regardless of cancer grade was observed for CALM2, DRD5, ICAM1, while EGR1, HRH1, HRH2, HRH3 were overexpressed." (PMID 34768392, 2021). "Given the lack of evidence regarding the trans-activation effects of EGR1 and USF2 on the SIRT1 promoter in cancer, we focused on investigating the trans-activation effects of these two transcription factors." (PMID 31068761, 2019). "Moreover, in cells expressing the cancer-derived K57N mutant (termed K57N cells), MEK1(K57N), ERK, and rpS6 were persistently phosphorylated and therefore Egr1 was constitutively expressed irrespective of EGF stimulation." (PMID 35831322, 2022). "Egr-1 is thought to activate and positively regulate NDRG1 in a variety of cancers; however, in GBM, Egr-1 was not involved in the regulation of NDRG1 expression, indicating that HIF might be the main regulator." (PMID 35448004, 2022).